IGFBP3 (insulin like growth factor binding protein 3)
Diseases named in the same sentence as IGFBP3 in open-access papers (continued):
Sharing a sentence is not in itself a finding about the gene and the disease.
ischemic stroke (7 papers, 2017 to 2023). A stroke disorder caused by obstruction of blood flow to the brain, due to thrombotic (local blood clot formation) or embolic (due to a blood clot or other material traveling from another site) event. "Among all of the predicted gene targets, IGFBP3 was chosen as a candidate because it is reported to be associated with ischemic stroke." (PMID 32312329, 2020). "Methylation of AMH, C17orf82, HDAC9, IGFBP3, LRRC10B, PDE3A, PRDM6, SYT7 and TBX2 was significantly associated with ischemic stroke." (PMID 35345488, 2022). "Higher methylation levels of 18 targets in AMH, C17orf82, HDAC9, IGFBP3, LRRC10B, PDE3A, PRDM6, SYT7 and TBX2 genes were associated with a lower risk of ischemic stroke." (PMID 35345488, 2022). "According to the results from stage one and stage two, we confirmed that higher methylation levels of 17 targets in AMH, C17orf82, HDAC9, IGFBP3, LRRC10B, PDE3A, PRDM6, SYT7 and TBX2 genes were associated with a lower risk of ischemic stroke." (PMID 35345488, 2022). "In agreement with our findings, decreased IGFBP3 expression was negatively correlated with miR‐27‐3p level in blood samples drawn from ischemic stroke patients." (PMID 32312329, 2020). "The two type miRNAs together with IGF-1/IGFBP3 may contribute to the progression of ischemic stroke, which remains for further investigation." (PMID 30361294, 2018). "The results showed that the mean methylation levels of AMH, C17orf82, HDAC9, IGFBP3, LRRC10B, PDE3A, PRDM6, SYT7 and TBX2 were significantly (Wilcoxon's two sample test) lower in ischemic stroke cases than in controls." (PMID 35345488, 2022). "In addition, IGFBP3 and HDAC9 have been found to be related to poor prognosis in patients with ischemic stroke." (PMID 35345488, 2022).
liver cancer (7 papers, 2010 to 2024). An epithelial or non-epithelial malignant neoplasm that arises from the liver. "In a case–cohort study within a cohort of 29 133 male smokers we examined associations of serum IGF-I and IGF binding protein (IGFBP)-3 with liver cancer (50 cases)." (PMID 20717109, 2010). "Low IGF-I and IGFBP-3 levels in male smokers are associated with increased risk of liver cancer." (PMID 20717109, 2010). "Because the activation of IGF signaling is characteristic for HB and IGFBP3 suppression contributes to the sustainment of IGF signaling, we wanted to determine the role of the IGFBP3 gene in the biology of pediatric liver cancers." (PMID 22401581, 2012). "Strengths of this investigation include the prospective study design of the ATBC Study, in which IGF-I and IGFBP-3 were measured from blood samples collected at the baseline visit, preceding the development of liver cancer." (PMID 20717109, 2010). "We also observed associations between 131 proteins and risk of liver cancer that included IGFBP7 and IGFBP3 [1.65 (1.48–1.84) and 0.46 (0.39–0.54), respectively], and 51 proteins and risk of kidney cancer, such as HAVCR1 and ESM1 [2.88 (2.55–3.24) and 1.84 (1.55–2.19)]." (PMID 38750076, 2024). "The IGF1 to IGFBP3 molar ratio represents the level of active IGF1, and patients with an IGF1 concentration higher than their IGFBP3 level are at an increased risk of liver cancer." (PMID 29113370, 2017). "This study provides the first direct evidence that the reactivation of IGFBP3 decreases aggressive properties of pediatric liver cancer cells and that IGFBP3 promoter methylation might be used as an indicator for vessel-invasive tumor growth in HB patients." (PMID 22401581, 2012). "In conclusion, findings from this study suggest that IGF-I and IGFBP-3 may have independent roles in development of liver cancer." (PMID 20717109, 2010). "We observed significant nonlinear associations between IGF-I and IGFBP-3 and liver cancer risk, with the strongest association seen in the lowest IGF range." (PMID 20717109, 2010). "In this study, we investigated the role of the insulin-like growth factor binding protein 3 (IGFBP3), a known competitor of the IGF axis, in pediatric liver cancers." (PMID 22401581, 2012). "Treatment of all five liver cancer cell lines with trichostatin A resulted in the strong demethylation and reexpression (data not shown) of IGFBP3, comparable to the effect communicated by 5-Aza-dC but in a much shorter period (24 h)." (PMID 22401581, 2012). "We conducted a case–cohort study to assess the independent roles of IGF-I and IGFBP-3 in liver cancer aetiology in a population without preexisting diseases that are known risk factors." (PMID 20717109, 2010). "IGFBP-3 levels did not alter the association between serum IGF-I and risk of developing liver cancer." (PMID 20717109, 2010). "Nevertheless, our functional data clearly show that IGFBP3 silencing is not just a cell culture artifact, but instead, it plays an important role in driving adverse growth characteristics of liver cancer cells originating from advanced stages of liver tumor development." (PMID 22401581, 2012). "Age-adjusted logistic regression analyses show a significant nonlinear association between liver cancer risk and serum IGF-I and IGFBP-3 (P<0.05 and P<0.01, respectively), suggesting some curvature to the relationship between risk and IGF levels such that the ORs vary across the range of IGF values." (PMID 20717109, 2010).
renal cell carcinoma (7 papers, 2009 to 2023). "In the human renal cell carcinoma cell line Caci-2 that was derived from a primary tumor, IGFBP3 stimulates proliferation." (PMID 34046336, 2021). "Insulin-like growth factor 1 (IGF1) and IGF binding protein 3 (IGFBP3) play an important role in the development and progression of renal cell carcinoma (RCC)." (PMID 27976731, 2016). "High IGF1/IGFBP3 ratio at diagnosis shows better prognosis in renal cell carcinoma." (PMID 37088808, 2023). "In addition, among various common tumours, IGFBP3 mRNA levels were increased most significantly in renal cell carcinoma." (PMID 34512163, 2021).
systemic sclerosis (7 papers, 2012 to 2025). A chronic disorder, possibly autoimmune, marked by excessive production of collagen which results in hardening and thickening of body tissues. "Serum IGFBP-3 was higher in systemic sclerosis than in controls, and elevated IGFBP-3 levels were related to a lower incidence of telangiectasia in systemic sclerosis." (PMID 34646335, 2021). "Increased levels of IGFBP-3 have been observed in primary skin fibroblast cultures from systemic sclerosis (SSc) patients." (PMID 41226289, 2025). "Syndecan-2 and tenascin, profibrotic genes that are increased in lung tissues of patients with systemic sclerosis or IPF, are induced in fibroblasts by TGF-β in an IGFBP-3-dependent manner or by IGFBP-3 alone." (PMID 30018981, 2018).
adenoma (6 papers, 2008 to 2025). A neoplasm arising from the epithelium. "The levels of IGF-1, the ratio of IGF-1/IGFBP-3, and insulin have been found to be associated with adenomas and advanced adenomas." (PMID 39509387, 2024). "Second, we conducted an analysis of subgroups according to sex, treatment method and adenoma size, since pituitary adenomas possess diverse clinical manifestations, and the IGFBP3 gene may be associated with a specific subtype." (PMID 30290787, 2018). "Low expression of tissue IGFBP-3 mRNA correlated with increased risk of adenomas." (PMID 18498652, 2008). "Low expression of IGFBP-3 mRNA in normal colonic mucosa predicts increased risk of adenomas." (PMID 18498652, 2008). "Our observed association between high tissue IGFBP-3 mRNA and reduced risk of adenomas may therefore reflect different or indirect effects of IGFBP-3 on apoptosis." (PMID 18498652, 2008). "Our findings suggest that local IGFBP-3 in the colon may directly increase adenoma risk but IGFBP-3 may act through a pathway other than apoptosis to influence adenoma risk." (PMID 18498652, 2008). "We tested the hypothesis that low levels of plasma or tissue IGFBP-3 will predict increased risk of adenomas and low apoptosis in normal colonic mucosa." (PMID 18498652, 2008). "The differential association of tissue IGFBP-3 versus plasma IGFBP-3 with adenoma risk suggests that local IGFBP-3 may better correlate with the functional effects in colonic tissue compared with systemic levels." (PMID 18498652, 2008). "Array data mining found that genes such as Ccnb1, Igfbp3, Nusap1, Pttg1, Racgap1, Top2a, Tpx2, which are associated with the aggressive behaviour of various human tumors, including PAs, and proto-oncogenes such as Ect2, Kit, Kras, Lyn, Ret are up-regulated in rat adenomas." (PMID 23756599, 2013). "We divided plasma or tissue IGFBP-3 values into quartiles based on the distribution in controls and evaluated the association between quartiles of plasma or tissue IGFBP-3 and adenomas." (PMID 18498652, 2008). "Compared to controls, adenoma subjects had significantly lower apoptosis and lower tissue IGFBP-3 mRNA." (PMID 18498652, 2008). "Subjects in the lowest three quartiles of tissue IGFBP-3 gene expression were more likely to have adenomas." (PMID 18498652, 2008). "Similarly, IGFBP3 was significantly higher in adenomas relative to adenocarcinomas (3.34 vs. 3.09, p = 0.002) with 67% of paired samples showing a decline in IGFBP3 expression upon progression to malignancy (p = 0.002)." (PMID 40699620, 2025). "Our findings suggest that low local IGFBP-3 expression may increase adenoma risk but is not likely to mediate the relationship between adenomas and apoptosis." (PMID 18498652, 2008). "We assessed whether plasma or tissue IGFBP-3 would predict the risk of colorectal adenomas or low apoptosis in normal colonic mucosa among adenoma cases and non-adenoma controls." (PMID 18498652, 2008). "However, to our knowledge, no studies have previously evaluated tissue IGFBP-3 mRNA in normal colonic mucosa in relation to adenoma risk." (PMID 18498652, 2008). "Together these data suggest that low levels of tissue IGFBP-3 may increase adenoma risk but is not likely to mediate the association between low apoptosis and increased risk of adenomas." (PMID 18498652, 2008). "A recent study reported CDX2 as a transcriptional repressor of IGFBP-3, accordingly, it is possible that CDX2 and other factors interact with IGFBP-3 in the colon to promote adenoma development." (PMID 18498652, 2008). "Very few human studies, have investigated tissue IGFBP-3 in the human colon and to our knowledge none have assessed the relationship between tissue IGFBP-3 mRNA, adenomas and apoptosis." (PMID 18498652, 2008).
depression (6 papers, 2015 to 2023). "The model adjusted for age, depression, education, history of tobacco use and alcohol use, and IGFBP-3 level was also significant (n=104 for the adjusted model), OR 0.24 (0.06-0.98)." (PMID 27744417, 2016).
diabetic cardiomyopathy (6 papers, 2022 to 2025). Diabetic cardiomyopathy is a disorder of the heart muscle in people with diabetes. "Prior studies have demonstrated that inhibition of IGFBP3 promotes angiogenesis and mitigates cardiac fibrosis and remodeling in mice with diabetic cardiomyopathy." (PMID 40271123, 2025). "Suppressing IGFBP3 expression in mice with diabetic cardiomyopathy can alleviate cardiac fibrosis and enhance cell proliferation while inducing AKT and ERK phosphorylation; this potentially plausible signaling pathway needs to be explored further." (PMID 35154570, 2022).
diabetic nephropathy (6 papers, 2020 to 2024). "Subsequent investigations added a role of IGFBP6 and IGFBP3 in other kidney diseases such as diabetic nephropathy, glomerulosclerosis, and IgA nephropathy." (PMID 39081308, 2024). "The strongly upregulated genes IGFBP1 and IGFBP3 have been suggested as markers for diabetic nephropathy and chronic kidney disease." (PMID 32197499, 2020). "IGFBP-3 confers a pro-apoptotic effect in diabetic nephropathy." (PMID 37331957, 2023). "The pro-apoptotic effect of IGFBP-3 is also reflected in diabetic nephropathy." (PMID 35002740, 2021).
growth failure (6 papers, 2008 to 2024). "Our study shows significant inverse relationships between the SIRT1 concentration and the IGF-1 levels, the IGF-1/IGFBP-3 molar ratio and the degree of growth deficiency." (PMID 39062007, 2024). "Growth hormone (GH) resistance - characterized by GH hypersecretion, and low serum levels of growth hormone binding protein, insulin-like growth factor I (IGF-I), and insulin-like growth factor binding-protein 3 (IGF-BP3) - has also been related to growth failure in AN patients." (PMID 23029058, 2012). "The child with a history of: growth failure or a documented growth deceleration, associated with: nystagmus or impaired vision and reduced serum concentrations of IGF-1 and IGFBP-3 should be considered GH deficient (or GH-inhibited), even with normal provocative tests." (PMID 20108502, 2008). "The first is clinically characterized by severe postnatal growth failure and facial dysmorphism, and biochemically by normal-to-elevated circulating GH concentrations but deficiencies in circulating Insulin-like Growth Factor 1 (IGF-1) and Insulin-like Growth Factor Binding Protein 3 (IGFBP-3)." (PMID 29025428, 2017). "In this report, we described a child referred to our Pediatric Endocrinology Department for a severe growth failure, in presence of low IGF-1 and IGFBP-3, but normal GH levels." (PMID 29025428, 2017).
hepatoblastoma (6 papers, 2005 to 2024). Hepatoblastoma (HB) is a malignant hepatic tumor and is the most common pediatric liver cancer. "The UHRF1/HAUSP/DNMT1 complex was also detected on the promoters of HHIP and IGFBP3, two key TSGs in hepatoblastoma, and this interaction caused the inhibition of these genes." (PMID 33922029, 2021). "IGFBP3 is also downregulated in the majority of hepatoblastoma primary tumors and is implicated in HCC drug resistance." (PMID 33669204, 2021). "It was found that IGFBP3 is expressed at low levels in a hepatoblastoma (HB) cell line and in HB primary tumors while it is expressed at high levels in normal liver tissues." (PMID 33669204, 2021). "Deletion, mutagenesis, and methylation constructs of IGFBP-3 promoter were assessed in the human hepatoblastoma cell line HepG2 for promoter activity." (PMID 15661074, 2005). "Interestingly, the depletion of UHRF1, but not of its partner HAUSP, significantly increased the expression of the HHIP and IGFBP3 genes and decreased the H3K9me2 mark at the HHIP and IGFBP3 TSG loci, leading to the inhibition of hepatoblastoma cell growth." (PMID 33922029, 2021). "The IGFBP3 levels were very low or undetectable in human HCC samples compared with non‐neoplastic liver tissue which are 4‐ to 100‐fold higher than in HCC49 and IGFBP‐1 and IGFBP‐2 were also decreased in hepatoblastoma." (PMID 32798252, 2020). "Employing chromatin immunoprecipitations (CHIP), one study has suggested that E3 ubiquitin-like containing PHD and RING finger domain 1 (UHRF1) may play a crucial role in the profound silencing of tumor suppressor genes (TSGs) such as HHIP, IGFBP3, and SFRP1 in hepatoblastoma." (PMID 38390281, 2024).
Impaired glucose tolerance (6 papers, 2016 to 2025). An abnormal resistance to glucose, i.e., a reduction in the ability to maintain glucose levels in the blood stream within normal limits following oral or intravenous administration of glucose. "In this regard, previous studies have shown that overexpression of IGFBP3 is associated with impaired glucose tolerance." (PMID 36353242, 2022). "On the other hand, an overexpression of IGFBP3 concurred with impaired glucose tolerance, and an increase in IGFBP3 was associated with a higher risk of T2D in women." (PMID 34646401, 2021).
sarcopenia (6 papers, 2022 to 2024). Progressive decline in muscle mass due to aging which results in decreased functional capacity of muscles. "IGF-1 and IGFBP3 blood concentrations were found to be reduced in older adults with sarcopenia and were significantly associated with muscle mass and IHG strength." (PMID 38616362, 2024). "Our findings demonstrate a positive correlation between IGFBP-3 and appendicular lean mass, suggesting a protective role of IGFBP-3 in sarcopenia by promoting muscle mass and reducing the likelihood of sarcopenia development." (PMID 39507055, 2024). "Elevated levels of IGF-1, IGF-1R, IGFBP-3, and IGFBP-7 within the IGF family are associated with a decreased risk of sarcopenia, indicating a causal associated with sarcopenia." (PMID 39507055, 2024). "As a result, we successfully identified a causal effect between IGF family members and sarcopenia, with higher levels of IGF-1, IGF-1R, IGFBP-3, and IGFBP-7 being associated with a reduced risk of sarcopenia." (PMID 39507055, 2024). "IGFBP3 and UCP2 are both related to muscle phenotypes associated with sarcopenia, an age-related loss of muscle function." (PMID 36003146, 2022). "Furthermore, a cross-sectional analysis involving 131 elderly individuals revealed a noteworthy decrease in IGFBP-3 levels among patients with sarcopenia, implying a contrasting function of IGFBP-3 compared to IGF-1 in skeletal muscle." (PMID 39507055, 2024). "As for the ratio IGF-I/IGFBP3, it was the most associated with several LC- and the VLC-NEFA which might suggest the implication of IGF-I in the mechanisms related to sarcopenia." (PMID 36658632, 2023). "In addition to IGF-1, within the IGF family, we found that IGF-1R increased whole body fat-free mass, and IGFBP-3 and IGFBP-7 increased appendicular lean mass, and improved muscle mass and muscle bulk, demonstrating that high IGF-1R, IGFBP-3, and IGFBP-7 levels may reduce the risk of sarcopenia." (PMID 39507055, 2024).
type 1 diabetes (6 papers, 2012 to 2023). "Reduced concentrations of IGFBP-3 have been associated with Type 1 diabetes mellitus (T1DM), and its levels have been shown to have a positive correlation with HbA1c, total cholesterol, and LDL-cholesterol levels while inversely correlating with blood pressure." (PMID 37834128, 2023). "The exact mechanisms by which type 1 diabetes (T1D) and poor glycemic control relate to the GH-axis and its interaction with IGF-1 and IGFBP-3 remain to be determined." (PMID 33905470, 2020). "We have previously demonstrated that IGFBP-3 inhibited REC apoptosis in cells cultured in high glucose and in samples from type 1 diabetic rat retinas." (PMID 23592916, 2013). "In type 1 diabetes, where IGF-I and IGFBP-3 levels are decreased, substitutive rhIGF-I/IGFBP-3 therapy enhances protein and glucose metabolism by controlling both endogenous glucose output and peripheral glucose uptake." (PMID 23148873, 2012).
acute lymphoblastic leukemia (5 papers, 2018 to 2023). Leukemia with an acute onset, characterized by the presence of lymphoblasts in the bone marrow and the peripheral blood. "Insulin-like growth factor binding protein-3 (IGFBP3) has been noted to be frequently downregulated in acute lymphocytic leukemia (ALL) cells." (PMID 29495357, 2018). "In acute lymphoblastic leukemia, resveratrol inhibits cell proliferation and viability by downregulating the levels of miR-196b and miR-1290, both of which directly regulate the expression of insulin-like growth factor-binding protein 3 (IGFBP3)." (PMID 33066509, 2020). "For instance, in patients with acute lymphoblastic leukemia (ALL), a study demonstrated that the expression of IGFBP3 was decreased in ALL patients." (PMID 33680956, 2020). "Resveratrol significantly reduced miR-196b/miR-1290 expression in the T-ALL (T-cell acute lymphoblastic leukemia) TTL-104 and B-ALL (B-cell acute lymphoblastic leukemia) SUP-B15 cell lines and upregulated the expression of IGFBP3." (PMID 33680956, 2020).